BRAF (B-Raf proto-oncogene, serine/threonine kinase)
Diseases named in the same sentence as BRAF in open-access papers (continued):
Sharing a sentence is not in itself a finding about the gene and the disease.
acute myeloid leukemia (23 papers, 2015 to 2026). Acute myeloid leukemia (AML) is a group of neoplasms arising from precursor cells committed to the myeloid cell-line differentiation. "Although RAS/MAPK pathway mutations affecting NRAS, KRAS, and/or PTPN11 are common in de novo or acute myeloid leukemia (AML)-myelodysplasia-related (MR), BRAF variants rarely occur in AML." (PMID 39596583, 2024). "Of the cases of BRAF V600E-mutant acute myeloid leukemia (AML) that have been described, most display monocytic morphology and concurrent KMT2A rearrangement." (PMID 39596583, 2024). "While manifestations of LCH improved after blocking BRAF by dabrafenib treatment, the BRAF wt CCUS progressed to acute myeloid leukemia (AML)." (PMID 35004300, 2021). "Interestingly, we observed that six out of seven patients with acute myeloid leukemia (AML) exhibited AML with monocytic differentiation, and all the patients with AML exhibited an extremely poor prognosis compared to those without BRAF mutations." (PMID 38791222, 2024).
conjunctival melanoma (23 papers, 2008 to 2025). "Patients with BRAF-mutated metastatic conjunctival melanoma have shown objective responses to BRAF inhibition in several reported cases but not in all." (PMID 32718045, 2020). "Mutations in BRAF are identified in 25–35% of conjunctival melanoma of which the vast majority is the BRAF V600E mutation." (PMID 33396957, 2020). "BRAF mutations occur frequently in conjunctival melanoma, especially in the sun-exposed area of the bulbar conjunctiva." (PMID 33396957, 2020). "V-raf murine sarcoma viral oncogene homolog B1 (BRAF) V600E mutation characterizes up to 50% of conjunctival melanomas as an early event in tumor development." (PMID 31683701, 2019). "In vivo, several BRAF mutated conjunctival melanomas were effectively treated with BRAF inhibitors in monotherapy or in combination with MEK inhibitors." (PMID 31683701, 2019). "Herein, we report a case of a 70-years old patient with a metastatic conjunctival melanoma harboring V600E BRAF mutation successfully treated with dabrafenib and trametinib." (PMID 31024839, 2019). "This could explain the higher frequency of BRAF-V600E mutations found in conjunctival melanoma published in other studies, closer to the cutaneous one." (PMID 35159047, 2022). "However, recent genetic studies and molecular profiling indicated the presence of BRAF mutation in approximately 30% of conjunctival melanoma." (PMID 33964953, 2021). "BRAF mutations were more often identified in conjunctival melanoma with a bulbar localization." (PMID 33396957, 2020). "Moreover, mutations in BRAF were detected in only one iris melanoma, whereas BRAF mutations are common in conjunctival melanoma." (PMID 33396957, 2020). "Besides immunotherapy, treatment with BRAF(/MEK) inhibitors should be considered in metastatic BRAF-mutated conjunctival melanoma and can even be considered in the (neo)adjuvant setting." (PMID 32718045, 2020). "Other uncommon BRAF mutations are detectable in <6% of conjunctival melanomas." (PMID 31683701, 2019). "Notably, the frequent BRAF (B-Raf proto-oncogene, serine/threonine kinase) mutation in conjunctival melanoma opens possibilities for targeted therapies, such as BRAF inhibitors, offering promising options for management alongside traditional surgical approaches." (PMID 39006575, 2024). "However, it was eventually shown that BRAF mutations are present in conjunctival melanomas." (PMID 27520988, 2016). "In patients with conjunctival melanoma, which involves dysregulation of the MAPK and PI3K/AKT/mTOR pathways, mutations in BRAF, NRAS, and NF1 are commonly observed, while KIT and PTEN mutations occur less frequently." (PMID 41001300, 2025). "Reported cases of targeted molecular inhibitor therapy in locally advanced, recurrent or metastatic BRAF mutant conjunctival melanoma cases." (PMID 40831998, 2025). "Genetic diagnostic methods are becoming more widely applied, both for inherited diseases (such as neurofibromatosis type 1) and for tumours (eg, BRAF testing in cutaneous and conjunctival melanoma)." (PMID 36161831, 2022). "BRAF-mutant conjunctival melanomas usually occur in young males and present with pigmented cells more frequently than BRAF wild-type conjunctival melanomas." (PMID 31683701, 2019). "In view of the recent development of effective BRAF and MEK inhibitors, the presence of BRAF V600 mutations in conjunctival melanomas is of considerable therapeutic relevance." (PMID 29559732, 2018). "For instance, BRAF V600E and NF1 mutations occur more frequently in conjunctival melanomas." (PMID 39564955, 2024). "BRAF and NRAS mutations may be risk factorsfor recurrence and shorter survival in conjunctival melanoma, which wouldmake these patients candidates for targeted therapies and comprehensive andindividualized follow-up." (PMID 35544941, 2023).
conjunctival melanoma (continued). "However, it is genetically similar to CM based on associated BRAF and NRAS mutations, thus therapies effective at treating CM appear to have clinical benefits in conjunctival melanoma." (PMID 33964953, 2021). "BRAF mutation is not frequently observed in other types of MM, thus conjunctival melanoma representing a molecularly distinct MM subtype." (PMID 33964953, 2021). "Data on the survival of patients with metastatic conjunctival melanoma is limited but seems poor, with a median overall survival of 5–8 months, although survival is likely to have improved after BRAF(/MEK) inhibitors and immune checkpoint inhibitors became available." (PMID 32718045, 2020). "Iris melanoma, also originating from the uvea, has similarities to the genetic makeups of both posterior uveal melanoma (UM) and conjunctival melanoma since mutations in GNAQ and GNA11 are less common and genes involved in conjunctival melanoma such as BRAF have been described." (PMID 33396957, 2020). "Most relevant for current practice is the absence of BRAF mutations in posterior uveal melanoma, although present in some iris melanomas and conjunctival melanomas." (PMID 32718045, 2020). "More recent reports suggest that disseminated conjunctival melanoma may be responsive to targeted molecular therapies, such as BRAF and MEK inhibitors in BRAF-mutant tumors, and checkpoint inhibitor immunotherapeutic agents, such as pembrolizumab." (PMID 33194647, 2020). "Mutations in the CM driver genes BRAF and NRAS have been found in conjunctival melanoma." (PMID 31382694, 2019). "Moreover, BRAF-mutant conjunctival melanomas are more common on the bulbar than extrabulbar conjunctiva." (PMID 31683701, 2019). "About 30% of BRAF- and 43% of NRAS-mutant conjunctival melanomas show gains of their oncogenic loci." (PMID 31683701, 2019).
diffuse astrocytoma (23 papers, 2011 to 2024). A low-grade (WHO grade II) astrocytic neoplasm. "The molecular alterations of these “pediatric-type” grade II diffuse astrocytomas were recently described and concerned the BRAF p.V600E mutation, FGFR1 alterations or MYB or MYBL1 rearrangement." (PMID 32771057, 2020). "IDH1 wild-type diffuse astrocytoma most frequently harbor BRAF p.V600E mutations, accounting for ~40% of cases." (PMID 32164789, 2020). "The BRAF mutation should be routinely detected in all gangliogliomas even in cases in which IDH mutation suggests diffuse astrocytoma." (PMID 30984614, 2019). "This patient (ruled out as having Neurofibromatosis type 1) was diagnosed at the age of 4 with a diffuse astrocytoma of the optical nerve, which was positive for the BRAF V600E mutation and presented a recurrence, 3 years later, that also was positive for BRAF V600E." (PMID 30558563, 2018). "Among IDH-wild-type grade II diffuse astrocytomas, the TERT promoter mutation was the most common mutation found in the brain (67%, 4/6) compared to BRAF p.V600E (14%, 2/14) mutation in the spine (Fisher test: p = 0.037)." (PMID 32771057, 2020). "These include diffuse astrocytoma, MYB- or MYBL1-altered; diffuse low-grade glioma, MAPK pathway-altered; polymorphous low-grade neuroepithelial tumor of the young (BRAF mutations and FGFR2 fusions); and infant-type hemispheric glioma (alterations in NTRK, ROS1, ALK, or MET)." (PMID 37509316, 2023). "Unlike intracranial diffuse astrocytomas, intramedullary diffuse astrocytomas are rarely IDH-mutated and can harbor BRAF mutations." (PMID 39199553, 2024). "These alterations have also been described in the adult age group where they represented ~50% of so-called isomorphic diffuse glioma (a subtype of IDH1 wild-type, BRAF p.V600E negative diffuse astrocytoma) in both children and adults." (PMID 32164789, 2020). "Whilst PA4 contained the BRAF fusion, PA1 contained the STGAL1-WHSC1 fusion together with further complex rearrangements as shown by whole genome sequencing, which may account for this tumour clustering with the diffuse astrocytomas." (PMID 27229157, 2016).
nodular melanoma (23 papers, 2016 to 2025). "In our previous study done with RT-PCR in nodular melanoma patients in Indonesia, central location and lymphovascular invasion were correlated with BRAF V600 mutation." (PMID 32188503, 2020). "Along with the other associations, this trend suggests that Indonesian nodular melanoma cases with the BRAF V600 mutation tend to have worse prognoses than cases with the wild-type BRAF." (PMID 32188503, 2020). "Studies from Caucasian populations, such as Australia and the United States, Germany, and Norway, report prevalence of BRAF V600 mutations in nodular melanomas at 22.37%, 37.7%, and 40.84%, respectively." (PMID 31890008, 2019). "Given the lack of evidence for Indonesian populations, further research is needed to elucidate the prevalence of the BRAF V600 mutation and its associations with clinicopathologic parameters among nodular melanoma cases in Indonesia." (PMID 31890008, 2019). "A study in Japan reported that 50% of nodular melanoma cases had the BRAF V600 mutation, while another research in Turkey stated the percentage at 29.4%." (PMID 31890008, 2019). "The BRAF V600 mutation was found in 4 patients, yielding a prevalence of 10% among nodular melanoma cases." (PMID 31890008, 2019). "In contrast, NRAS mutations were more commonly found in nodular melanomas (19.4%) compared to either BRAF mutant (8.6%) or WT tumors (15.3%)." (PMID 27191502, 2016). "Patients harboring BRAF mutations were younger (median age 51 years), predominantly male, and most frequently were diagnosed with nodular melanoma subtype—a pattern that aligns with previous cohorts where nodular melanoma is commonly associated with BRAF mutations." (PMID 40994966, 2025). "In this study, the BRAF V600 mutation was found in 53.85% of the nodular melanoma cases." (PMID 32188503, 2020). "In Brazil, 80% nodular melanomas had the BRAF V600 mutation." (PMID 31890008, 2019). "A 31-year-old female (patient 10A) was initially diagnosed with stage IIIc BRAF V600E positive nodular melanoma on the skin of the buttock." (PMID 40136348, 2025). "Most lesions (75.7%) were nodular melanoma, 66.4% were ulcerating, 12% presented as multiple lesions at the initial diagnosis, and 5.7% were BRAF mutant samples." (PMID 36980512, 2023). "A 31-year-old female (patient 10A) was initially diagnosed with stage IIIc BRAF V600E positive nodular melanoma to the skin of buttock." (PMID 37398360, 2023). "We also observed that 24.1% of NRAS-mutant tumors proved to be nodular melanoma, while 16.7% of BRAF-mutant and 17.9% of double-wild-type tumors belonged to that histological category." (PMID 34209415, 2021). "The outcomes of our research are especially at odds with the result of our previous study using RT-PCR, which report a 10% BRAF V600 prevalence among Indonesian nodular melanomas." (PMID 32188503, 2020). "A 63-year old male who presented in July 2016 with a 4.2 mm BT ulcerated BRAF wild-type nodular melanoma on his right upper back." (PMID 30107850, 2018). "For instance, convolutional neural networks can be applied to hematoxylin and eosin slides and then paired with mutational status information like BRAF V600E or NRAS Q61 to distinguish between biologically distinct subsets of superficial spreading and nodular melanoma." (PMID 41283484, 2025). "We present the case of a patient who was diagnosed in 2018 with nodular Malignant Melanoma (MM) without BRAF V 600 mutations stage 3 C (pT4b pN1a M0), and who underwent adjuvant citokines treatment with Interferon alpha 2b-48 weeks." (PMID 38248787, 2024).
mucinous tumors (22 papers, 2010 to 2025). "The current study aimed to determine the frequency of the BRAF V600E mutation in ovarian serous and mucinous tumors, including borderline and carcinoma subtypes." (PMID 37600581, 2023). "While most studies have found BRAF mutation in serous tumors, it has been reported to be less infrequent in mucinous tumors." (PMID 37600581, 2023). "This is at odds with previous publications that have shown increased rates of MMR deficiency, RAS and BRAF mutations in mucinous tumours." (PMID 35265523, 2022). "In particular, we found a significant relationship between BRAF V600E mutations and histopathological features (p < .01) for mucinous tumors." (PMID 33145020, 2020). "RCC (vs. LCRC) was more frequently observed with higher frequencies of MSI-high (MSI-H) and BRAF mutations in female and younger patients, and was closely associated with metastasis, poor differentiation, and mucinous tumors." (PMID 32161617, 2020). "For instance, serous borderline tumors or low-grade serous ovarian carcinoma (LGSOC) are characterized by frequent KRAS or BRAF mutations while mucinous tumors carry KRAS mutations and endometrioid ovarian tumors harbor PTEN mutations." (PMID 30478449, 2019). "Some authors advocate that the anatomical location, histology and grading of the primary lesions has a relevant prognostic role, especially because BRAF mutations have been more frequently observed in right-sided, poorly differentiated mucinous tumors." (PMID 27737711, 2016). "Compared with conventional adenocarcinomas, mucinous tumors tend to be associated with young age, advanced tumor stage, and distinct molecular patterns, such as microsatellite instability and mutations of the BRAF and KRAS genes." (PMID 26081940, 2015). "KRAS and BRAF mutations are mutually exclusive in CRC: the shortage of BRAF mutations detected in appendiceal neoplasms with PMP seems to be a consistent consequent high prevalence of KRAS mutations among appendiceal mucinous neoplasms." (PMID 33712927, 2021). "Serous tumors and some mucinous tumors may show BRAF and K-RAS mutations." (PMID 22995373, 2012). "Like MOTs, colorectal mucinous carcinomas are the only group in which frequent KRAS and BRAF mutations are found; mutations in both genes are absent in breast and rare gastric mucinous carcinomas, and appendiceal mucinous tumors are BRAF wild type." (PMID 26257827, 2015). "Activating KRAS mutations are more common in mucinous tumours than in all other histological types 17, 34, while no mucinous tumours have been found to harbour a BRAF mutation." (PMID 26800494, 2016). "BRAF mutations were also associated with mucinous tumors: BRAF mutations occurred in 28% of grade 3 mucinous tumors (>50% mucinous tumor cells) but in only 9.4% of the non-mucinous tumors (grade 1 and 2)." (PMID 20233444, 2010). "Unlike mucinous tumors, high grade serous tumors typically do not express BRAF and KRAS mutations." (PMID 33946684, 2021). "KRAS, BRAF and SACT prior to HIPEC; HIPEC chemotherapy type (oxaliplatin or mitomycin); poor and/or mucinous tumour differentiation; and the presence of signet cells in tumour did not significantly predict OS (p > 0.05)." (PMID 36400886, 2023).
mucinous tumors (continued). "Age, gender, synchronous or metachronous metastases, preoperative laparotomy or laparoscopy, PCI ≥ 20, TN-stage, primary tumour location, mucinous tumors, grade of differentiation, and the presence of KRAS or BRAF mutations were also analyzed but none was significantly associated with lead time." (PMID 36117176, 2022).